MIR448 (microRNA 448)
Synonyms: hsa-mir-448; MIRN448; miRNA448
Gene: MicroRNA gene on chromosome X (114,823,454 to 114,823,564, forward strand). Ensembl gene ENSG00000199001.
Gene Ontology:
Biological process: miRNA-mediated post-transcriptional gene silencing; negative regulation of cell differentiation; negative regulation of fat cell differentiation; negative regulation of translation
Cellular component: RISC complex
Homologues: Orthologues: chimpanzee ptr-mir-448 (100% identical), macaque mml-mir-448 (98% identical), rat Mir448 (96% identical), mouse Mir448 (95% identical), dog MIR448 (94% identical), guinea pig MIR448 (88% identical), rabbit MIR448 (70% identical).